BLCAP (BLCAP apoptosis inducing factor)
Description:
Modulates expression of genes involved in the regulation of proliferation, cell cycle and apoptosis.
Synonyms: Bc10
Tractability: Antibody: UniProt predicts a signal peptide or a membrane-spanning region.
Gene: Protein-coding gene on chromosome 20 (37,492,472 to 37,528,100, reverse strand). Ensembl gene ENSG00000166619.
Subcellular location: Cytoplasm; Nucleus; Membrane
Subcellular location (Human Protein Atlas): Nucleoli
Gene Ontology:
Molecular function: protein binding
Biological process: apoptotic nuclear changes
Cellular component: cytoplasm; membrane; nucleus
Genetic constraint (gnomAD): Loss-of-function variants: 1 observed, 5.85 expected, observed/expected ratio (o/e) 0.17, 90% interval 0.06 to 0.81. That is too few expected variants to judge how well the gene tolerates losing a copy. Missense variants: 66 observed, 112.03 expected, observed/expected ratio (o/e) 0.59, 90% interval 0.48 to 0.72. Synonymous variants: 48 observed, 52.02 expected, observed/expected ratio (o/e) 0.92, 90% interval 0.73 to 1.17.
Homologues: Orthologues: chimpanzee BLCAP (100% identical), dog BLCAP (100% identical), macaque BLCAP (100% identical), mouse Blcap (100% identical), pig BLCAP (100% identical), rabbit BLCAP (100% identical), rat Blcap (100% identical), guinea pig BLCAP (98% identical), zebrafish blcap (90% identical), tropical clawed frog blcap (87% identical), Drosophila melanogaster bc10 (51% identical), Caenorhabditis elegans Y73E7A.6 (39% identical).
Diseases named in the same sentence as BLCAP in open-access papers:
BLCAP is named in the same sentence as 46 diseases in open-access papers, as found by Europe PMC text mining. Sharing a sentence is not in itself a finding about the gene and the disease. The quoted sentences say what the papers report.
bladder cancer (17 papers, 2010 to 2025). "A-to-I RNA editing of the bladder cancer-associated protein BLCAP promotes bladder cancer cell proliferation." (PMID 39794701, 2025). "Chen found that ADAR1 edits multiple sites in the YXXQ motif of BLCAP (a tumor suppressor for bladder cancer), causing it to lose its inhibition of STAT3 activation, thereby promoting tumorigenesis in cervical cancer (CC)." (PMID 36895481, 2023). "Another significant CpG site cg15440392 is located within BLCAP, which encodes a bladder cancer-associated protein." (PMID 28067321, 2017). "Given that we previously found that nuclear localization of BLCAP was associated with disease outcome in bladder cancer, we also examined the effect of nuclear localization of BLCAP on disease outcome." (PMID 23049907, 2012). "Bladder Cancer Associated Protein (BLCAP, formerly Bc10), was identified by our laboratory as being down-regulated in bladder cancer with progression." (PMID 23049907, 2012). "Bladder cancer-associated protein (BLCAP) is a highly conserved protein among species, and it is considered a novel candidate tumor suppressor gene originally identified from human bladder carcinoma." (PMID 19908260, 2010). "DNA methylation patterns such as protein tyrosine kinase 2 (PTK2) hypermethylation have been found to be associated with overall survival, whereas bladder cancer associated protein (BLCAP) hypomethylation is strongly associated with recurrence and cancer-specific death risk." (PMID 40282460, 2025). "In addition to expression, cellular localization patterns of BLCAP have been reported to be associated with survival of bladder cancer patients and breast cancer patients with lobular carcinomas." (PMID 36461044, 2022). "The expression level of the bladder cancer-associated protein (BLCAP), which is an apoptosis-related tumor suppressor identified from bladder cancer, was significantly higher (29.2-fold; p < 0.05) in NaB-treated HT1376 cells than that in cells without NaB treatment." (PMID 34943506, 2021). "Despite the fact that the role of editing events within BLCAP are still unknown, it has been proposed that this protein is a novel prognostic biomarker in bladder cancer and it is associated with cell proliferation." (PMID 23697632, 2013). "Metabolic associations with genes known to associate with bladder cancer (BLCAP), ovarian cancer (OCIAD1), and infertility caused by azoospermia (DAZAP1) could highlight the importance of integrating both methylation and metabolomics for assessing T2D complications." (PMID 37679740, 2023). "Nonetheless, poor survival of bladder cancer patients correlates with strong nuclear expression of BLCAP, which is impacted by the interaction of BLCAP and Signal Transducer and Activator of Transcription 3 (STAT3) in the JAK/STAT-pathway." (PMID 37055532, 2023). "While BLCAP is reported as a novel STAT3 interaction partner in bladder cancer, and A-to-I editing of BLCAP mRNA loses the inhibitory regulation of STAT3 activation in cervical cancer." (PMID 35574370, 2022). "The direction of correlations in our analysis of cell line data was consistent with earlier reports of associations of increased BLCAP protein expression and lower BLCAP promoter methylation with inferior survival of bladder cancer patients." (PMID 36461044, 2022). "However, compared with the related normal tissues, BLCAP edited isoforms were reduced in astrocytoma, bladder cancer and colorectal cancer, indicating that the RNA editing level of BLCAP differs in different tumors." (PMID 35898396, 2022).
bladder cancer (continued). "Angela Gallo's team found that editing of the BLCAP transcript was downregulated in astrocytomas, bladder cancer and colorectal cancer, while other groups reported a general elevation of editing levels in cancerous tissues such as liver, brain, oral cavity and lung." (PMID 28455960, 2017). "Moreover, we observed a general decrease in BLCAP-editing level in astrocytomas, bladder cancer and colorectal cancer when compared with the related normal tissues." (PMID 19908260, 2010). "As one of the representative substrates of A-to-I RNA editing identified in 2005, BLCAP was reported to show an obvious difference in editing level between tumor and normal tissues, with a tumor-specific editing pattern in lung cancer, oral cavity cancer, brain cancer and urinary bladder cancer." (PMID 28455960, 2017). "Although the number of patients in our analysis was limited (n = 189; corresponding to 65 events), and the effect on disease outcome was very modest, the trend is similar to what we have observed for bladder cancer, suggesting that BLCAP may have multiple functions, with tissue and cell-specificity." (PMID 23049907, 2012). "While BLCAP has been reported to be a tumor suppressor gene promoting apoptosis, its product interacts with STAT3 and has been suggested to promote bladder cancer progression." (PMID 36461044, 2022). "In addition, although the level of BLCAP hyper-editing showed a statistically significant difference between normal and tumoral urinary bladder cancer tissues, RNA editing did not participate in the evolution of urinary bladder cancer as observed through the analysis of nine editing substrates." (PMID 28455960, 2017).
cervical cancer (9 papers, 2017 to 2025). A primary or metastatic malignant neoplasm involving the cervix. "Another example of a hyper-edited transcript can be a tumor suppressor gene, bladder cancer-associated protein (BLCAP), which promotes cell proliferation in cervical cancer and hepatocellular carcinoma." (PMID 39641903, 2025). "Taken together, these results show a correlation among the three novel editing sites in BLCAP coding sequence, and suggest that the editing pattern may be associated with pathogenesis of cervical cancer." (PMID 28455960, 2017). "Lost expression or degradation of BLCAP is observed in urothelial, renal, and cervical cancer, osteosarcoma, colorectal carcinoma, and human tongue carcinoma." (PMID 37055532, 2023). "In cervical cancer, once a tumor-suppressor BLCAP is edited, it loses its ability to interact with and inactivate STAT3, thereby increasing cell proliferation." (PMID 36895481, 2023). "In cervical cancer (CC), ADAR1 promotes tumorigenesis by editing multiple sites within the YXXQ motif of bladder cancer-associated protein (BLCAP), a tumor suppressor." (PMID 30619092, 2018). "In this present investigation, we detected the mRNA expression of ADAR1 and ADAR2 in paired-cervical tissues by realtime-PCR and analyzed their correlation with BLCAP editing as well as cervical cancer." (PMID 28455960, 2017). "Herein, we analyzed the coding sequence of BLCAP transcripts in 35 paired cervical cancer samples using high-throughput sequencing." (PMID 28455960, 2017). "These date suggest that ADAR1 plays a more important role than ADAR2 in BLCAP A-to-I RNA editing and the progression of cervical cancer." (PMID 28455960, 2017). "Herein, we used high-throughput DNA sequencing instead of direct sequencing to provide a more thorough description of the A-to-I RNA edited sites of BLCAP in cervical cancer." (PMID 28455960, 2017). "We previously published data from in vitro and in vivo experiments indicated that BLCAP might be a potential anti-tumor gene in cervical cancer." (PMID 28455960, 2017). "Our work delineate the underlying molecular mechanisms of BLCAP-mediated inhibition of STAT3 in cervical cancer, and we hypothesis that BLCAP may act as a new potential therapeutic target for various types of STAT3-activated carcinomas." (PMID 28455960, 2017). "Results indicated that both ADAR1 and ADAR2 were involved in BLCAP editing, while ADAR1 played a more important role in BLCAP editing as well as cervical cancer." (PMID 28455960, 2017). "Further studies revealed that BLCAP interacted with signal transducer and activator of transcription 3 (STAT3) and inhibited its phosphorylation, while A-to-I RNA editing of BLCAP lost the inhibition to STAT3 activation in cervical cancer cell lines." (PMID 28455960, 2017).
hepatocellular carcinoma (5 papers, 2017 to 2025). A malignant tumor that arises from hepatocytes. "In addition, the RNA edited BLCAP gene was found to stably promote cell proliferation, suggesting that the RNA over-editing of BLCAP may serve as a novel potential driver in advanced hepatocellular carcinoma." (PMID 28455960, 2017).
astrocytoma (4 papers, 2010 to 2023). "Remarkably, in astrocytoma, the human bladder cancer-associated protein (BLCAP) transcript showed decreased editing." (PMID 37958449, 2023). "When we analyzed the editing of the endogenous BLCAP transcript in astrocytoma cell lines, we observed a baseline editing activity of 0–4.2% at the Y/C, Q/R and K/R sites in all 4 control cell lines (U118, U118 EGFP, A172 and A172 EGFP)." (PMID 19908260, 2010). "We found that ∼5% of the total BLCAP transcripts were edited in the untransfected or control astrocytoma cell lines transfected with pEGFP." (PMID 19908260, 2010). "In addition, despite our small cohort of tumors samples, we observed that a correlation exists between a decrease in ADAR-mediated RNA editing on BLCAP transcript and the histological grade of malignancy in pediatric astrocytomas." (PMID 19908260, 2010). "We therefore analyzed the editing events in both the exonic and intronic regions of BLCAP in normal brain, brain tumor (astrocytoma grade IV) and astrocytoma cell lines untransfected and transfected with the editing enzyme ADAR2 as ADAR2 edited most of the exonic sites studied at a higher level." (PMID 19908260, 2010). "As ADAR2 can edit all 3 sites within the coding region of BLCAP in HEK 293T cells, we expected an increase in editing levels at these sites in astrocytoma cell lines transfected with EGFP-ADAR2." (PMID 19908260, 2010).
breast carcinoma (3 papers, 2012 to 2022). "To investigate the miRNA-related functions of MALAT1 in breast cancer, we chose miR-339-5p as a model miRNA for further studies, with a particular focus on the target gene BLCAP." (PMID 30683807, 2019). "We show here that BLCAP protein overexpression defines a subset of breast carcinomas with unfavorable outcome." (PMID 23049907, 2012). "IHC analysis of formalin-fixed paraffin-embedded (FFPE) sections from tumor specimens showed a wide variation in the patterns of BLCAP expression in breast cancer." (PMID 23049907, 2012). "To evaluate the potential of BLCAP as possible breast cancer biomarker and prognostic factor, we investigated the expression and distribution pattern of BLCAP in breast tissue, normal as well as malignant, using this antibody." (PMID 23049907, 2012). "With this in mind we evaluated the potential of BLCAP, a marker we previously identified in urothelial carcinomas, as possible breast cancer biomarker and prognostic factor." (PMID 23049907, 2012). "We also analyzed BLCAP expression and prognostic value using a set of tissue microarrays comprising an independent cohort of 2,197 breast cancer patients for which we had follow-up clinical information." (PMID 23049907, 2012). "Survival analysis performed by the Cox proportional hazards model using BLCAP nuclear localization as dichotomous variable (nuclear staining or not) showed no prognostic value (HR = 1.18 [95%CI 0.80–1.74]) of nuclear localization of BLCAP in breast cancer." (PMID 23049907, 2012). "In conclusion, we found that expression of BLCAP was up-regulated in a substantial proportion of breast tumors indicating that BLCAP may be of value as a biomarker for breast cancer." (PMID 23049907, 2012). "By contrast, breast cancer specimens with no detectable immunoreactivity for BLCAP, constituted only a minor part of the total number of samples (8 out of 101 samples)." (PMID 23049907, 2012). "To study changes in the pattern of BLCAP expression that might take place during progression from normal mammary epithelium to breast cancer, we analyzed a reference set of specimens collected from 123 patients that are part of the breast proteomics initiative within DCTB." (PMID 23049907, 2012).
bladder tumors (2 papers, 2012 to 2022). "In addition to the differences in cellular expression and localization of BLCAP in normal tissue, we also found that the pattern of BLCAP expression in malignant tissue was very different in breast and in bladder tumors." (PMID 23049907, 2012). "Additionally, BLCAP was discovered to interact with STAT3 physically and may involve the STAT3-mediated progression of precancerous lesions to invasive bladder tumors." (PMID 35063012, 2022).
lobular carcinomas (2 papers, 2012 to 2022). "A Cox proportional hazards model analysis showed an enhanced hazard of death (HR = 1.84 [95%CI 0.98–3.48]) for the group of women with lobular carcinomas with nuclear BLCAP expression." (PMID 23049907, 2012). "After adjusting for the influence of several variables (age, tumor size, BRE grade, and lymph node status), BLCAP nuclear presence in lobular carcinomas retained independent, albeit modest, prognostic value (P = 0.042)." (PMID 23049907, 2012). "We examined the effect of BLCAP nuclear localization on overall survival in lobular carcinomas using BLCAP nuclear expression as dichotomous variable (nuclear staining or not)." (PMID 23049907, 2012). "Since we found that nuclear expression of BLCAP was associated with ILCs (P = 0.0018 by Fisher’s exact test), we examined further the effect of nuclear localization of BLCAP on disease outcome specifically in lobular carcinomas." (PMID 23049907, 2012).
Obesity (2 papers, 2013 to 2025). Accumulation of substantial excess body fat. "Neuronatin (NNAT) is a paternally expressed imprinted gene residing within a large intron of the bladder cancer associated protein (BLCAP) gene, variations in which are implicated in extremes of childhood and adult obesity." (PMID 23527188, 2013).
osteosarcoma (2 papers, 2012 to 2023). A usually aggressive malignant bone-forming mesenchymal neoplasm, predominantly affecting adolescents and young adults. "BLCAP is ubiquitously expressed in different tissues, and several studies have found differential expression of BLCAP in various cancer types, such as cervical and renal cancer, as well as human tongue carcinoma and osteosarcoma." (PMID 23049907, 2012). "Further studies by other laboratories have all found downregulation of BLCAP gene expression in the various cancer types examined, such as cervical, and renal cancer, as well as human tongue carcinoma, human osteosarcoma, and α-radiation-induced rat osteosarcoma." (PMID 23049907, 2012).
preeclampsia (2 papers, 2022 to 2025). Preeclampsia is a hypertensive disorder of pregnancy that is characterized by new-onset hypertension with proteinuria presenting after 20 weeks of gestation, and depending on mild or severe forms may initially present with severe headache, visual disturbances, and hyperreflexia. "DMR2 spans Bladder cancer-associated protein (BLCAP), a known differentially methylated gene in the placenta associated with preeclampsia, and the maternally imprinted Neuronatin (NNAT) locus has raised expression in the severely preeclamptic placenta." (PMID 41286963, 2025). "For example, DMR2 which spans across BLCAP and NNAT shows an unambiguous DNA methylation reduction in blood from preeclampsia-exposed children, whereas with DMR4, the region just downstream of the DMR has DNA methylation split into three clusters." (PMID 41286963, 2025).
breast tumors (1 paper, 2012). "Expression of BLCAP in breast tumors was examined, using an automated cellular imaging system (ACIS) (see methods section), by quantitative IHC analysis of FFPE sections of all tissue blocks available from the DCTB 123 patient dataset." (PMID 23049907, 2012). "2D Western blots of BLCAP-overexpressing COS1 cells and a breast tumor sample, T63, were reacted with the BLCAP C-term antibody (respectively), which resulted in an analogous pattern in both samples." (PMID 23049907, 2012). "However, it is more likely that although the relative expression levels of BLCAP are increased in breast tumor cells, the absolute levels of expression remain below the threshold for cytotoxicity." (PMID 23049907, 2012). "Indeed, we found that 28 cases out of 62 (45.2%), for which we had matched pairs of normal and malignant tissue with interpretable staining results for BLCAP, displayed an increase in BLCAP expression of more than 1.5-fold in breast tumor cells compared to normal cells." (PMID 23049907, 2012).
cervical (1 paper, 2017). "Although the anti-tumorigenic role of BLCAP has been examined in preliminarily studies, the relationship between BLCAP function and A-to-I RNA editing in cervical carcinogenesis still require further exploration." (PMID 28455960, 2017). "Then we focused our attention on the three most highly edited sites to investigate the role of BLCAP A-to-I RNA editing in cervical carcinogenesis." (PMID 28455960, 2017).
chronic myelogenous leukaemia (1 paper, 2021). "The upregulation of ADAR1 in the prostate, liver, chronic myelogenous leukaemia (CML), colorectal and cervical cancers has been found to target cancer-related mRNAs such as DHFR, BLCAP, and RRUNE1." (PMID 34638933, 2021).
iron deficiency (1 paper, 2024). "Additionally, differential methylation involving LRRC32 and BLCAP/NNAT were previously linked to exposure to adverse perinatal factors (e.g., viral infection, iron deficiency, birth asphyxia) with potential neuropsychiatric consequences." (PMID 38503926, 2024).
lymph node metastasis (1 paper, 2012). "We obtained interpretable, quantifiable staining results for BLCAP in a total of 205 specimens, comprising 73 normal, 101 tumor, and 31 lymph node metastasis tissue samples." (PMID 23049907, 2012).